APOE (apolipoprotein E)
Diseases named in the same sentence as APOE in open-access papers (continued):
Sharing a sentence is not in itself a finding about the gene and the disease.
atherosclerosis (continued). "However, the formation of C1q-ApoE complexes was seen within Aβ plaques and arteries and correlated with cognitive impairment and atherosclerosis." (PMID 38255891, 2024). "Li Showed that Akkermansia muciniphila could guard against atherosclerosis by inhibiting inflammation in ApoE−/− mice." (PMID 39451408, 2024). "Next, we analyzed the effect of Met on HFD-induced atherosclerosis in ApoE KO mice." (PMID 39223261, 2024). "Furthermore, animal experiments have shown that PFOS can accelerate the progression of atherosclerosis in ApoE - -mice, possibly through the activation of macrophage NF-κB, leading to M1 polarization and inflammation." (PMID 39850378, 2024). "Study on apoE−/− mice proved that liraglutide reduced atherosclerosis." (PMID 39741663, 2024). "However, IR+/−/ApoE−/−/Nox2−/y mice had more atherosclerosis in the thoracoabdominal aorta compared to IR+/−/ApoE−/−/Nox2+/y mice." (PMID 39401163, 2024). "Suppressing CD73 with siRNA decreased atherosclerosis and plaque formation by reducing migration, proliferation, and foam cell transformation of vascular smooth muscle cells (VSMCs) via reducing CyclinD1 expression and serum lipid levels in ApoE-/- mice." (PMID 39735551, 2024). "Notably, after 8 weeks of HFD, fulminant atherosclerosis was present in both APOE cKO and D374Y strains, whereas the aortic roots of control mice were healthy, as expected." (PMID 39196121, 2024). "Upregulation of IRF3 expression has been observed in the endothelial cell layer of atherosclerotic arteries and macrophages in atheromatous plaques from patients with coronary heart disease and hyperlipidaemic ApoE-/- mice (mice with HFD-induced atherosclerosis)." (PMID 38164186, 2024). "Besides effects on myeloid cells, P. gingivalis infection increased Th17 cells but downregulated Treg cells in ApoE-/- mice on high-fat diet, along with increasing atherosclerosis." (PMID 39717783, 2024). "An atherosclerosis model was established by feeding ApoE-/- mice with high-fat chow." (PMID 39525632, 2024). "Further, injection of polyclonal immunoglobulin preparations into ApoE-/- mice resulted in a reduction in fatty streaks and fibrous plaques, indicating that atherosclerosis could be inhibited." (PMID 39399488, 2024). "ApoE−/− mice have been frequently used in atherosclerosis research." (PMID 38790704, 2024). "Anti-CD47 treatment reduces vascular inflammation in human patients and ameliorates atherosclerosis in hypercholesterolemic ApoE−/− mice by correcting defects in efferocytosis and normalizing the clearance of diseased vascular tissue, leading to the regression of atherosclerosis." (PMID 39926714, 2024). "Given our findings that LXN is enriched in plaques and colocalizes with macrophages in atherosclerotic lesions, we further determined whether LXN expression in macrophages regulates atherosclerosis in ApoE-/- mice." (PMID 39424784, 2024).
atherosclerosis (continued). "To test this hypothesis we used a mouse model of hyperglycemia-induced atherosclerosis, the ApoE−/−:Ins2+/Akita mouse." (PMID 38339098, 2024). "However, animal (mice) studies have shown that APOE ‘knock-out’ mice experience cognitive impairment, severe dyslipidemia, and atherosclerosis." (PMID 38673634, 2024). "ApoEST2 DKO mice with attenuated ILC2 had significantly worse atherosclerosis than ApoE KO mice." (PMID 38674885, 2024). "They showed that in ApoE KO mice carrying a mutation in the gene for ferroportin (FPN), which disrupts the hepcidin/FPN interaction, iron accumulation in the vessel wall exacerbated atherosclerosis." (PMID 38727367, 2024). "It is quite likely that there is an optimal range of ApoE plasma levels, and that levels above or below that range impose a risk rather than a benefit for atherosclerosis." (PMID 38429638, 2024). "ApoE produces pleiotropic effects in various human diseases, from AD to atherosclerosis." (PMID 38396791, 2024). "Hereto, atherosclerosis-susceptible male apolipoprotein E knockout mice were fed a low-fat diet with or without 10 mg/kg/day LXR agonist T0901317 supplementation for 8 weeks." (PMID 38672446, 2024). "This significantly lessened atherosclerosis induced by the apolipoprotein E (apoE) -/- mice diet." (PMID 39463572, 2024). "Notably, in an apoE−/− mouse model of atherosclerosis, a 4-week WTD induced profound inflammatory reprogramming of circulating innate immune cells and their bone marrow progenitors, which persisted despite switching back to regular diet." (PMID 39493874, 2024). "High-fat diet-induced atherosclerosis in ApoE KO mice is reduced in IKKε KO mice." (PMID 39261656, 2024). "Apolipoprotein-E-deficient mice with FABP4 deficiency did not develop atherosclerosis from a high-cholesterol diet." (PMID 37794302, 2024). "On the other hand, for flaxseed oil revealed anti-atherosclerosis action on high-fat diet-induced ApoE−/− mice, the acetic acid and propionic acid in feces were negatively correlated with seven bacteria (Intestinimonas, Oscillibacter, Lachnoclostridium, Bilophila, Enterorhabdus, etc.)." (PMID 39403395, 2024). "Previous studies have demonstrated that CAWS vasculitis caused chronic inflammatory cell infiltration, predominantly of macrophage cells, at the aortic root in an ApoE−/− atherosclerosis mouse model and that statins markedly reduced inflammatory cell infiltration in animal experiments." (PMID 39424429, 2024). "Studies from multiple groups, including the author’s, have demonstrated that the evolution of atherosclerosis in ApoE-/- mice is paralleled by infiltration of inflammatory cells and progressive loss of mobility of BMMNCs with reduced levels of angiogenic factors including SDF-1." (PMID 38275616, 2024). "Furthermore, the absence of TIMP-3 has been demonstrated to polarize macrophages and intensify inflammation in atherosclerosis, as evidenced in ApoE null mice." (PMID 39195176, 2024). "The ApoE-/- mouse model is extensively used in atherosclerosis research." (PMID 38558816, 2024). "The patients with either apoE gene mutations or apoE deficiency develop the type III hyperlipoproteinemia, which exhibits mild hyperlipidemia but is predisposed to the premature development of atherosclerosis." (PMID 39087075, 2024).
atherosclerosis (continued). "Consequently, in this study, we fed ApoE-/- mice with high-fat diet to establish atherosclerosis model for 16 weeks with noninvasive ultrasound of small animals." (PMID 38498570, 2024). "Therefore, the present study is the first to demonstrate that Met-induced enhancement of telomere function is attenuated in atherosclerosis in ApoE KO mice." (PMID 39223261, 2024). "Similarly, in a mouse model (ApoE−/−) of high-fat diet-induced atherosclerosis, the delivery of adenovirus LOX-1 siRNA was found to increase the fibrous cap thickness and reduce the number of macrophages recruited in the atherosclerotic lesion." (PMID 38790688, 2024). "In order to confirm this assumption, ApoE knockout (KO) mice, the most popular animal model for human atherosclerosis, were fedwith a western diet and injected with an adenovirus (Ad)-SFRP4 or an Ad-green fluorescent protein (GFP) adenovirus through the tail vein for 12 weeks." (PMID 37143778, 2023). "CUMS has previously been shown to aid in the development of atherosclerosis in ApoE-/- mice." (PMID 37692113, 2023). "To further investigate the transcriptomic effects of PDGFD in the disease setting, we treated the lineage tracing atherosclerosis ApoE-/-mouse model with a murine derived inhibitory monoclonal antibody directed against Pdgfd (25E17, PD-ab) or with a control IgG (Ctl-ab)." (PMID 36792607, 2023). "Our novel findings are in principle agreement with previous reports of our group demonstrating that PACAP deficiency accelerates and aggravates atherosclerosis in ApoE−/− mice, whereas PAC1 deficiency attenuates the progression of atherosclerosis in ApoE deficient mice." (PMID 37980508, 2023). "Recently, a novel plaque-targeted nano-GLP-1RA (GlpNP) drug has been designed, synthesized and injected at very low doses twice a week for six weeks in ApoE-/- mice to allow decoupling of systemic effects in effort to understand the impact of direct plaque delivery on atherosclerosis." (PMID 37401947, 2023). "Therefore, we next determined the effects of KB administration on the life span of high‐fat diet (HFD)‐fed ApoE−/− mice with atherosclerosis‐related organ damage." (PMID 37060184, 2023). "We previously reported that the ligature around the molars of ApoE-deficient mice, not that of WT mice, exacerbated the arterial wall lipid deposition and atherosclerosis." (PMID 37628753, 2023). "Not surprisingly, consistent with the Morrbid expression in monocytes from CAD patients, the expression of Morrbid was increased in bone marrow-derived monocytes from ApoE mice with atherosclerosis compared with that in monocytes from wild-type normal control mice." (PMID 37426471, 2023). "TMAO showed positive effects against atherosclerosis in ApoE-/- transgenic mice." (PMID 37337893, 2023). "The present study applied atherosclerosis model mice (ApoE-/-) as the study subject, which may lead to species limitations and gene knockout limitations." (PMID 37692113, 2023). "Finally, pharmacologic inhibition of Gal-3 with MCP also led to reduced atherosclerosis in two studies in ApoE mice with fat diet." (PMID 38170009, 2023). "Therefore, the use of a suitable preclinical model prone to atherosclerosis development, such as LDL receptor- or ApoE-deficient mice, will be required to evaluate the beneficial effects of Totum-070 on atherosclerosis." (PMID 38140315, 2023). "Furthermore, infection with Usp14-expressing adenovirus halted the progression of atherosclerosis in apolipoprotein E (Apoe) KO mice." (PMID 36834633, 2023).
atherosclerosis (continued). "In this study, we demonstrated that CFI-400945, a selective inhibitor of PLK4, inhibited neointima formation of mouse carotid arteries resulting from complete carotid ligation but accelerated partial carotid ligation-induced atherosclerosis in ApoE−/− mice fed a high-fat diet." (PMID 36750553, 2023). "In the uremic atherosclerosis model using apoE−/− mice, a significant increase in aortic oxalate levels and serum levels of oxidative stress and inflammatory markers have been observed, suggesting a significant role for hyperoxalemia in promoting oxidative stress and systemic inflammation." (PMID 37371749, 2023). "Therefore, in this study, we aimed to investigate the effects of the oral administration of RS on blood lipids and vascular molecules involved in HFD-induced atherosclerosis in ApoE−/− female mice." (PMID 37998401, 2023). "To interrogate whether smooth muscle OGT plays a direct role in development of atherosclerosis, we next generated smOGTKO mice on an ApoE-/- atherosclerotic background." (PMID 37175604, 2023). "Exposure of ApoE−/− mice to 50 nm polystyrene nanoplastics (PS‐NPs) with a high‐fat diet explores the roles of macrophage and lipid metabolism disruption in micro‐ and nanoplastic‐induced atherosclerosis." (PMID 37144527, 2023). "In order to establish an atherosclerosis model, the ApoE−/− mice were given an HFD for 10 weeks." (PMID 37836404, 2023). "It was noted that the specific immune cell profiles observed in ApoE−/− mice could vary depending on factors such as age, diet, and the stage of atherosclerosis development." (PMID 37628966, 2023). "ApoE−/− mice fed with HFD were used to establish atherosclerosis model." (PMID 37371838, 2023). "To further clarify the mechanism underlying the preventive effects of SFN on macrophage foam cell formation and atherosclerosis progression, we collected PMs from ApoE−/− mice at the end of experiment and assessed their ox-LDL phagocytotic activities using Dil-labeled ox-LDL." (PMID 37432260, 2023). "Given the importance of EVs in cell-to-cell communication, we evaluated the impact that EVs isolated from the plasma of PLHIV (HIVposEVs) had on the development of atherosclerosis using a well-established atherogenic mouse model (i.e., apoE−/− mice fed a high fat/high cholesterol diet)." (PMID 37108729, 2023). "In this study, we irradiated 3 month old age-matched ApoE null male mice, which can develop both spontaneous and diet-induced atherosclerosis, to assess the acute and long-term effects of simGCRsim- (50, 100, 150 cGy) and γ-IR (100, 200, 400 cGy) on LV function and structure." (PMID 38054039, 2023). "Prior research has revealed that inhibiting PI3K activity could be a promising strategy for the treatment of atherosclerosis, as demonstrated by the reduction of plaque size in the ApoE−/− model upon PI3K gene deletion." (PMID 37174317, 2023). "We next investigated possible factors by which chronic LD shifts could increase atherosclerosis in female ApoE−/− mice." (PMID 37064902, 2023). "Therefore, this study aimed to further explore the roles of these CD11c+ B cells in atherosclerosis by utilizing both an ApoE−/− aged mouse model as well as CITESeq and scRNAseq to study these B-cell subpopulations in humans." (PMID 38259450, 2023). "Similar, another recent animal study suggested that iron overload could diminish atherosclerosis in apolipoprotein E knockout mice by interfering with hepatic CD36 and fatty acid binding proteins-mediated fatty acid uptake and transport." (PMID 37275636, 2023).
atherosclerosis (continued). "In addition, in a model of diabetic-induced atherosclerosis using ApoE knockout, inhibition of DRP1 reduced endothelial dysfunction, plaque formation, and smooth muscle cell calcification." (PMID 37175915, 2023). "BH4 supplementation has shown promise in preclinical models of atherosclerosis, inhibiting atherogenesis in apolipoprotein E knockout (ApoE-KO) mice fed a high-cholesterol diet, and reversing severe atherosclerosis in ApoE-KO mice with partial carotid ligation fed a high-fat diet." (PMID 37894881, 2023). "Additionally, the application of MI-2 via perivascular collars significantly hindered neointima development in C57BL/6J mice with complete carotid ligation, and atherosclerosis in ApoE−/− mice with partial carotid ligation on a high-fat diet." (PMID 38097554, 2023). "We examined whether the changes in development of spontaneous atherosclerosis observed in TG/ApoE−/− mice could be explained by the degree of macrophage infiltration into the arterial wall." (PMID 37628966, 2023). "In addition, alogliptin reduced atherosclerosis and inflammation, via inhibition of the monocyte activation/chemotaxis, in ApoE−/− mice." (PMID 37175496, 2023). "Similarly, it was shown that myeloid-specific PTP1B ablation decreases plaque formation and ameliorates dyslipidaemia in the ApoE−/− model of atherosclerosis." (PMID 37828508, 2023). "However, despite the apparent lack of alterations in plasma lipoproteins in our study, CETP expression nevertheless led to significantly increased atherosclerosis in the aortic arch regions and aortic roots of apoE−/− mice." (PMID 37004910, 2023). "Another study reports that the treatment of apolipoprotein E knockout (ApoE KO) mice with NAC orally for 8 weeks significantly attenuated the progression of atherosclerosis, with decreased plaque collagen content and nitrotyrosine expression, probably via a reduction in oxidative stress." (PMID 38136193, 2023). "However, studies on the anti-atherosclerosis effect of GEO and citral are limited, and it is on this basis that this study aims to examine the effect of GEO and citral in GAN diet/ʟ-carnitine-induced atherosclerosis ApoE−/− mice." (PMID 37210385, 2023). "APOE is involved in lipoprotein metabolism and participates in the activation of lipolytic enzymes, which is closely related to the occurrence and development of atherosclerosis." (PMID 37491214, 2023). "Utilizing in situ imaging and HE staining, we observed that the activation of the STING pathway led to an enlargement of the plaque area in both GSDME−/−/ApoE−/− and ApoE−/− mice, thereby counteracting the suppressive influence of GSDME deficiency on atherosclerosis progression." (PMID 37761020, 2023). "Atherosclerosis was induced in these ApoE knockout mice with the Western diet." (PMID 37426471, 2023). "In both female aorta surgical sample and bilateral ovariectomized female ApoE -/- mice samples, assay results indicated that estrogen prevented atherosclerosis through upregulating ESRα expression to induce ESRα-mediated activation of autophagy and reduce inflammation and cell pyroptosis." (PMID 36833280, 2023). "Because obesity, diabetes mellitus, and hyperlipidemia are crucial risk factors of atherosclerosis, metabolic parameters, including body weight, blood glucose, serum total cholesterol, and serum triglycerides were detected in ApoE−/− mice with atherosclerosis calcification." (PMID 38094889, 2023). "The findings signify that adropin treatment may alleviate the atherosclerosis in ApoE–/–/Enho–/– mice by inhibiting EndMT via the TGF-β/Smad2/3 signaling pathway." (PMID 37903785, 2023).